VEGFA (vascular endothelial growth factor A)
Diseases named in the same sentence as VEGFA in open-access papers (continued):
Sharing a sentence is not in itself a finding about the gene and the disease.
tumor (continued). "IRE1α signaling is known to be essential for angiogenesis and growth of tumor cells through VEGFA induction." (PMID 20221394, 2010). "For this reason, the primary stimulant of angiogenesis, vascular endothelial growth factor-A (VEGF), is an attractive target for tumor therapy." (PMID 24281102, 2010). "These processes are related, with hypoxia-inducible factors (e.g. VEGFA) secreted by hypoxic, perinecrotic tumor cells, resulting in the development of new vessels." (PMID 20838435, 2010). "Vascular endothelial growth factor-A (VEGF-A) is secreted by normal and tumor cells, with a significant portion bound to the endothelial surface and extra-cellular matrix." (PMID 24281094, 2010). "Vascular endothelial growth factor-A (VEGF) is a primary stimulant for tumor angiogenesis, making it a critical target for cancer therapy." (PMID 19888452, 2009). "Tumours promote angiogenesis by secreting factors, like vascular endothelial growth factor-A (VEGF-A), basic fibroblast growth factor (bFGF) and transforming growth factor (TGF)-β1." (PMID 19352388, 2009). "Delta-like ligand 4 (Dll4) is a Notch ligand that is upregulated by hypoxia and vascular endothelial growth factor-A (VEGF-A) and is reported to have a role in tumor angiogenesis." (PMID 19844231, 2009). "In brain tumours, one such parameter is vascular leakage, which is a response to tumour-derived vascular endothelial growth factor-A and can be measured by Gadolinium-DTPA (Gd-DTPA)-enhanced magnetic resonance imaging (MRI)." (PMID 18506183, 2008). "Vascular endothelial growth factor-A is widely regarded as the principal stimulator of angiogenesis required for tumour growth." (PMID 18349828, 2008). "Vascular endothelial growth factor-A (VEGF-A) has been demonstrated to play an important role in tumour angiogenesis and to influence prognosis in many cancers." (PMID 16641910, 2006). "Vascular endothelial growth factor-A, produced by tumour cells, inhibits the functional maturation of immune dendritic cells from haemopoietic progenitor cells." (PMID 12942123, 2003). "Vascular endothelial growth factor-A expression is elevated in tumours in response to a variety of stimuli, and its activity is largely restricted to vascular endothelial cells via two high-affinity receptors, Flt-1 (VEGF-R1) and KDR/Flk-1 (VEGF-R2)." (PMID 14612898, 2003). "Dynamic contrast-enhanced magnetic resonance imaging (DCE-MRI), using gadopentetate dimeglumine, was used to monitor acute effects on tumour vascular permeability following inhibition of vascular endothelial growth factor-A (VEGF-A) signal transduction." (PMID 14612898, 2003). "We propose that interleukin-6 indirectly promotes tumour angiogenesis through its up-regulation of the vascular endothelial growth factor-A load in platelets." (PMID 12454774, 2002). "Enrichment analysis highlighted key molecular changes in circRNAs that may influence angiogenesis and tumor progression, particularly the VEGFA-VEGFR2 pathway in TNBC." (PMID 41516402, 2026). "BMI1 induces the ubiquitination of histone H2A, which suppresses the expression of zinc finger protein 24 and decreases the secretion of vascular endothelial growth factor A, thereby promoting tumor angiogenesis and providing support for tumor cell proliferation and metastasis." (PMID 41268614, 2026). "Mechanistically, HYW: Normalized tumor vasculature: Restored the balance between proangiogenic and antiangiogenic factors (reduced VEGFA/bFGF, increased TSP-1/PF4), enhanced pericyte coverage and improved vascular maturity, and enhanced intratumoral perfusion (ultrasound imaging)." (PMID 42238595, 2026).
tumor (continued). "Conversely, HBEGF depletion can simultaneously downregulate VEGFA and markedly suppress tumor growth, indicating that HBEGF may be a more effective therapeutic target to disrupt this pro-angiogenic network." (PMID 41514936, 2026). "VEGFA is a critical regulatory factor that promotes tumor angiogenesis in HCC." (PMID 40726441, 2025). "Additionally, further investigation is required to verify if GPN3 modulates tumor angiogenesis through manipulation of VEGFA-VEGFR2 signaling, a crucial positive regulator of angiogenesis." (PMID 39893205, 2025). "To test this hypothesis, we introduced the STAT3 phosphorylation inhibitor Stattic into SLC9A2-knockdown tumor cells and observed that the upregulation of VEGFA induced by SLC9A2 knockdown was reversed." (PMID 40474298, 2025). "In summary, miRNAs can target and regulate TGFBR2, HIF1α, and VEGFA to inhibit tumor angiogenesis." (PMID 39857292, 2025). "GPR65-mediated suppression of tumor VEGFA production plays a prominent role." (PMID 39998425, 2025). "Furthermore, this population of neutrophils supports tumor invasion, angiogenesis, and metastasis by secreting VEGFA and MMP9." (PMID 40940764, 2025). "Melatonin exerts a tumor-suppressive effect by modulating the miR-424-5p/VEGFA axis." (PMID 40167762, 2025). "In PAK4KO tumours, this pathway’s activation may further compensate for diminished VEGFA signalling, promoting alternative vascular strategies that sustain perfusion and contribute to the observed pro-angiogenic and VM phenotypes." (PMID 41294859, 2025). "Stabilizes TRPM7 mRNA, increases VEGFA expression, promotes tumor angiogenesis." (PMID 40740874, 2025). "Furthermore, TAMs orchestrate the formation of TMEM doorways in collaboration with the tumour and endothelial cells, guided by VEGFA signalling, promoting tumour cell intravasation but also creating vascular niches potentially less accessible to T-cells." (PMID 40361472, 2025). "VEGFA antibodies reduce tumor vasculature, which led to the popular hypothesis that anti-VEGFA therapy could starve tumors by inhibiting angiogenesis." (PMID 40173050, 2025). "In PAK1KD cancer cells, the PPI network analysis highlighted significant changes in molecules involved in the VEGFA–VEGFR2 signalling pathway (reactome), which may underlie the reduced angiogenesis and enhanced vascular maturation observed in PAK1KD tumours." (PMID 41294859, 2025). "Furthermore, statin inhibition of NF-κB activation and signaling reduces transcription of pro-angiogenic genes e.g., VEGFA, decreased tumor growth, increased tumor necrosis and apoptosis." (PMID 40563926, 2025). "However, when used together, the combination treatment resulted in an even greater decrease in VEGFA expression, indicating a stronger inhibition of tumor blood vessel formation." (PMID 39949745, 2025). "Compared with the vector control, the overexpression of MMP28 significantly accelerated tumor growth, while the administration of the JNK inhibitor SP600125, the anti-IL-8 antibody MAB208-SP, or the anti-VEGFA antibody MAB293-SP inhibited tumor growth to varying degrees." (PMID 39972459, 2025). "Interestingly, despite this higher angiogenesis in PAK4KO tumours, the VEGFA expression in PAK4KO tumour cells was reduced compared to the WT, suggesting the primary role of fibronectin in promoting angiogenesis by the PAK4 knockout." (PMID 41294859, 2025). "Lastly, Lewis mouse transplant tumor experiments showed that SH inhibited tumor growth, reduced the protein expression of Ki-67, VEGFA and CD31 in transplanted tumor tissues, and the mRNA expression of MMP-2 and Bcl-2, while promoting the expression of Bax mRNA." (PMID 41444284, 2025). "Future studies should integrate longitudinal imaging with multi-region tumor sampling to determine whether VEGFA+ SC abundance correlates with progression." (PMID 40629113, 2025).
tumor (continued). "mRNA expression of CXCL9, iNOS, and IL-12β, anti-tumor macrophage markers, was elevated, while mRNA expression of IFNγ, TNFα, ARG-1, TGFβ, IL-10, and VEGFa, pro-tumor macrophage markers, was significantly lower in TAMs isolated from the prostates of RON∆Epi/TRAMP+ compared to RONF/F/TRAMP+ mice." (PMID 40282397, 2025). "Hence, cancer cells, through the overexpression of VEGFA, acquire the ability to affect, in turn, the immune and blood texture, shifting the tumor microenvironment (TME) towards an immune-suppressed microenvironment." (PMID 41373757, 2025). "Notably, FAP exhibited a positive correlation (r ≈ 0.4, p < 0.01) with genes involved in angiogenesis and tumor microenvironment remodeling, including VEGFA, HIF1α, and EGFR." (PMID 40430845, 2025). "AREG, EREG, and VEGFA are angiogenesis-related and often overexpressed in tumor cells." (PMID 40501071, 2025). "RUNX1 is an important regulator of tumour angiogenesis and invasion mediated through the upregulation of key molecules such as matrix metalloproteinases (MMPs) and vascular endothelial growth factor A (VEGFA)." (PMID 41573648, 2025). "Furthermore, TAMs promote tumor angiogenesis and immunosuppression by secreting various cytokines and angiogenic factors, such as vascular endothelial growth factor A (VEGF-A) and adrenomedullin (AMD)." (PMID 39744225, 2025). "m6A modifications play a critical role in regulating angiogenesis in NSCLC, where interactions between cancer-associated fibroblasts (CAFs) and m6A modifications are central in shaping the expression and stability of angiogenic factors such as VEGFA, crucial for tumor vasculature formation." (PMID 40740874, 2025). "In the current study, VEGFA was targeted by miR-205-5p in both tumor and endothelial cells." (PMID 40302796, 2025). "This approach to delivery may facilitate the application of CRISPR–Cas9 in the clinical management of cancer by concurrently blocking both autocrine and paracrine signaling of VEGFA in tumor cells." (PMID 40391083, 2025). "As vascular endothelial growth factor A (VEGFA), the downstream gene of ERRα, facilitates tumor angiogenesis and plays a role in drug targeting in RCC, whole-mount staining were performed to determine the effect of ERRα knockdown on vessel regeneration ability in RCC." (PMID 39820331, 2025). "Further mechanism studies showed that LRRC1 enhances PDK1 stability by promoting its deubiquitination via USP7, thereby increasing AKT1 phosphorylation levels and activating the AKT/GSK3β/β-catenin/VEGFA signaling pathway, ultimately accelerating tumor angiogenesis in HCC." (PMID 41369408, 2025). "Additionally, an in vivo study showed that APOC1 knockdown in nude mice reduced the expression of Ki67, CD31, and VEGFA in subcutaneous tumor tissues." (PMID 39873475, 2025). "Our study found that knockdown of CCN1 could cause the downregulation of VEGFA via the AKT pathway, which could lead to the suppression of tumor growth and angiogenesis." (PMID 40234387, 2025). "Hence, antiangiogenic therapies for CRC should focus on inhibiting the function of VEGFA in tumor angiogenesis." (PMID 40746889, 2025). "A trending increase in VEGFA was found after SA-HFIRE treatment across all days within the tumor." (PMID 39998766, 2025). "In the context of tumor progression, angiogenesis serves as a critical determinant of invasive and metastatic potential, driven by the overexpression of proangiogenic factors such as vascular endothelial growth factor A (VEGFA) in endothelial cells." (PMID 40986143, 2025). "Importantly, this angiogenic program appeared to diverge between tumor types: in dHpC tumors, VEGFA upregulation co-occurred with inflammatory gene expression, while in dCpH, it was coupled with oncogene activity, suggesting distinct regulatory mechanisms." (PMID 41279139, 2025).
tumor (continued). "Our preclinical assessment of the strategy showed that our HER2-VEGFA BsAbs exerted greater anti-metastasis activity against aggressive tumor models, leading to a greater survival benefit, than did the parental anti-HER2 and anti-VEGFA antibodies used alone or in simple combination." (PMID 40906526, 2025). "In addition, the western blot results indicated that VEGFA expression was notably increased in NSCLC tissues (T) compared with para-tumor tissues (N)." (PMID 39802612, 2025). "The undeniable role of VEGFA in tumor development is well-established." (PMID 39546272, 2025). "The risk score was positively correlated (r > 0.1) with VEGFA, VEGFB, and ICAM1, suggesting enhanced angiogenesis that may restrict immune infiltration and promote tumor progression." (PMID 41293172, 2025). "Furthermore, lactate produced by tumor cells has been shown to enhance the expression of genes such as VEGFA and Arg1 via HIF-1α, thereby promoting M2 macrophage polarization." (PMID 40129528, 2025). "Similarly, bevacizumab, an anti-VEGFA agent, has been shown to enhance tumor blood perfusion, reduce microvascular density, and lower interstitial fluid pressure in patients with colorectal cancer." (PMID 40173050, 2025). "USP13 downregulated VEGFA and inhibited tumor angiogenesis via the PTEN-AKT pathway." (PMID 40746889, 2025). "For example, they can release molecules that promote tumor angiogenesis, such as vascular endothelial growth factor-A (VEGF-A), transforming growth factor-β (TGF-β), heparin, interleukin-8 (IL-8), matrix metalloproteinase-9 (MMP-9), trypsin-like proteases, and chymotrypsin." (PMID 40703522, 2025). "In vitro experiments demonstrate that collagen stimulates tumor cells to express vascular endothelial growth factor A (VEGFA) and directly enhances vessel formation and endothelial cell proliferation through sex determining region Y box 18 (SOX18) upregulation." (PMID 39823457, 2025). "As a key mediator of angiogenesis, the upregulation of VEGFA may contribute to a pro-tumor microenvironment by enhancing tumor vascularization." (PMID 40536270, 2025). "Macrophages are the primary producers of numerous molecules that facilitate tumor angiogenesis, such as VEGFA, CXCL8 (chemokine (C-X-C motif) ligand 8), PlGF (placental growth factor), IL-1β (interleukin-1 beta), IL-6 (interleukin-6), TNF (tumor necrosis factor), MMPs, and cathepsins." (PMID 40940953, 2025). "Similarly, exosome-mediated angiogenesis, involving molecules like Wnt7b mRNA, VEGFA, and miR-381-3p, supports tumor vascularization and progression." (PMID 41154440, 2025). "In vivo experiments demonstrate that ASH2L‐K312‐lac promotes HCC malignant progression and is positively correlated with tumor microvessel density, and vascular endothelial growth factor A (VEGFA) is identified as the key mediator in ASH2L‐K312‐lac‐induced angiogenesis." (PMID 40726441, 2025). "Moreover, SLC9A2 reduces VEGFA secretion, normalizing tumor vasculature and reshaping the tumor microenvironment (TME), which ultimately enhances anti-tumor immunity." (PMID 40474298, 2025). "Targeting the integrin α2β1-CXCR4 complex and VEGFA could disrupt tumor-stroma interactions, reducing tumor proliferation." (PMID 40426238, 2025). "The first 3-D ST maps of osteosarcoma have uncovered discrete immune-evasion niches enriched for PD-L1+ osteoblastic cells, C1QC+ macrophages and VEGFA-driven endothelial networks that co-localise around necrotic bone trabeculae and at the invasive tumour–bone interface." (PMID 40740859, 2025). "Furthermore, VEGFA and bFGF levels were examined in the tumor tissues, showing a significant downregulation of both factors in PKN2 overexpressing tumors." (PMID 40515512, 2025). "Furthermore, ERPP treatment significantly attenuated tumor angiogenesis and downregulated the expression of the vascular endothelial growth factor A (Vegfaa) gene in the zebrafish xenograft model." (PMID 40863621, 2025).
tumor (continued). "However, a positive correlation was identified in molecules that promote tumor progression like VEGFA, ALDOA, and GPI." (PMID 40806276, 2025). "SIRT2 promotes tumor angiogenesis by regulating STAT3/VEGFA pathway." (PMID 40746889, 2025). "Furthermore, the expression of both CD-31 and VEGFA was decreased in tumor tissue after treatment with ASIV." (PMID 40362487, 2025). "Dual inhibition of VEGFA/VEGFC suppresses tumor growth, suggesting that combined VEGF targeting may enhance efficacy of ABCP in resistant NSCLC patients." (PMID 40843133, 2025). "Furthermore, this enhances the formation of new tumor blood vessels, with an increase of VEGFA expression, thereby increasing invasiveness and metastatic potential." (PMID 40282535, 2025). "Vascular endothelial growth factor A (VEGF-A) is a key driver of tumor angiogenesis." (PMID 39388711, 2025). "However, in tumors such as lung cancer, miR-126 can inhibit tumor angiogenesis by lowering VEGFA levels and activating signaling pathways such as Akt/mTOR/Erk1/2, ultimately suppressing tumor growth." (PMID 40332376, 2025). "In response to tumor microenvironments that lack the necessary oxygen or nutrients to thrive induce the production of angiogenic factors, namely vascular endothelial growth factor A (VEGFA)." (PMID 41327312, 2025). "Similarly, bevacizumab, a monoclonal antibody targeting vascular endothelial growth factor A (VEGF-A), demonstrated anti-tumor activity in a phase II trial of recurrent meningiomas." (PMID 40052125, 2025). "In HCC, VEGFA promotes the proliferation, migration, and invasion of endothelial cells, contributing to the formation of a dense network of blood vessels within the tumor." (PMID 39852395, 2025). "Moreover, circSNX6 knockdown led to decreased levels of circSNX6 and VEGFA expression, but increased miR-383-5p levels in the xenograft tumor samples (P < 0.05)." (PMID 38589413, 2024). "Monoclonal antibody therapy targeting VEGFA is a commonly used strategy in tumor treatment." (PMID 38687357, 2024). "In HCC, VEGFA is often overexpressed, leading to enhanced angiogenesis and tumor progression." (PMID 39682093, 2024). "Furthermore, the highest level of IL1B expression was observed in macrophages in ccRCC samples, and spatial transcriptome analysis revealed the colocalization of VEGFA+ MCs with IL1B+ macrophages at the tumor–normal interface." (PMID 39840068, 2024). "Pro-angiogenic factors perpetuate tumor blood vessel formation, with VEGFA being the most critical." (PMID 38716237, 2024). "The anti-angiogenic drug we used, VEGFR1-Fc, might also have some effects on regulating anti-tumor immunity, as it traps VEGFA, which could inhibit T cells and DCs, as well as promote Treg and MDSC expansion." (PMID 39335665, 2024). "The tumor-suppressing effect could be partially reversed by modulating miR-383-5p or VEGFA expression." (PMID 38589413, 2024). "Accordingly, we found that CXCL2+ CAFs may secrete complement C3 to interact with C1Q+ TAMs, mainly targeting the pro‐angiogenic gene VEGFA to maintain their M2‐like phenotype in chemoresistant tumours." (PMID 39422697, 2024). "The study of VEGFA expression in GC samples with various clinical stages and tumor grades showed that patients had a worse prognosis and that less differentiation of GC was followed by a greater level of VEGFA expression, particularly in the later stages of GC." (PMID 39457390, 2024). "High expression of VEGFA promotes tumor angiogenesis, which supports cancer development." (PMID 39840068, 2024). "That may be the result of multiple origin of TGF-β and VEGFA, but IL-10 is mainly produced by tumor infiltrated T cells." (PMID 38554155, 2024). "However, in terms of the ratio of TNF+ to VEGFA+ MCs, the ratios of tissues at the tumor core (1.8) and tumor rim (1.2) were significantly lower than those of adjacent normal tissues." (PMID 39840068, 2024).